CD4 (CD4 molecule)
Diseases named in the same sentence as CD4 in open-access papers (continued):
Sharing a sentence is not in itself a finding about the gene and the disease.
AIDS (continued). "Moreover, our study will help researchers to uncover the critical areas of correcting and dealing with multicollinearity when including both CD4 cell and viral load count in parametric multi-state modelling of HIV/AIDS, that many researchers have not been able to explore." (PMID 32228523, 2020). "We hypothesize that other variables might affect the heterogeneity, such as poor income adequacy, unemployment, homeless, lower CD4 counts, higher viral loads, the severity of depressive symptoms, duration of HIV/AIDS, poor self-efficacy and lack of social support." (PMID 29855289, 2018). "The World Health Organization (WHO) currently recommends initiation of ART in people living with HIV/AIDS at any CD4+ T cell count regardless of the WHO clinical stages, giving priority to those with severe or advanced HIV disease (WHO clinical stages III/IV) or a CD4 T cell count ≤350 cells/mm3." (PMID 30064395, 2018). "The Th17 cells studies in SM can be highlighted because, in spite of severe depletion of CD4+ T cells in the mucosal tissues during acute SIV infection, even in the face of high viral replication similar to infections by HIV-human and SIV-RM, they do not progress to AIDS." (PMID 26568963, 2015). "The median CD4 count at the first visit was 338 /μL (IQR 211–467) in the voluntary testing group, 292 /μL (IQR 147–408) in the screening group, 259 /μL (IQR 155–415) in the STI group, 234 /μL (IQR 122–392) in the non-AIDS disease group, and was the lowest in the AIDS group [54 /μL (IQR 23–98)]." (PMID 26606382, 2015). "Neither sex, prior AIDS-defining events, nor the year of ART initiation influenced the likelihood of adequate CD4+ cell count monitoring, though there was some indication that a CD4+ cell count less than 200 cells/μL at ART initiation may have had an effect." (PMID 26478610, 2015). "According to Ministry of Health (MoH) HIV/AIDS guidelines, all HIV-infected patients that present with a CD4 count result below 350 cells/μl, as well as all pregnant and lactating women, regardless of their CD4 count, should be initiated on antiretroviral therapy (ART)." (PMID 25767656, 2014). "Several questions were asked and mainly focused on; CD4 and CD8, Viral load and ESR, question of turning negative after treatment; health and giving birth to a health baby without HIV/AIDS as a sign to have treated HIV/AIDS and issues of mother to child transmission." (PMID 17257409, 2007). "Although we could not determine the CD4 T-cell count in order to elucidate the subjects' immune status, the HIV infection in these individuals were described as clinical stage 1 (asymptomatic), according to the revised WHO clinical staging of HIV/AIDS for adults and adolescents." (PMID 32523647, 2020). "However, CD4+ T cell loss cannot be the only pathogenic factor since severe opportunistic infections may develop in HIV infected patients with normal CD4+ T cell counts and since the recent START study indicated that absolute CD4+ T cell counts are not predictive for AIDS and non-AIDS events." (PMID 30459765, 2018). "Thus, IL-2 expansion of CD4+ Treg cells in HIV patients could not be expected to cure the deficit in conventional T cells seen in this disease nor contribute to decreasing the incidence of opportunistic infections and AIDS or non-AIDS-related malignancies." (PMID 22383042, 2012).
COVID-19 (2,143 papers, 2020 to 2026). A disease caused by infection with severe acute respiratory syndrome coronavirus 2. "Coronavirus Disease-2019 (COVID-19) can cause secondary bacterial and fungal infections by affecting the expression of pro-inflammatory markers, such as tumor necrosis alpha and certain cytokines, as well as the numbers of CD4 and CD8 cells." (PMID 35740209, 2022). "A closer examination of cell metabolism revealed a loss of connectivity between metabolic pathways in CD4 memory T cells after COVID-19." (PMID 41509309, 2026). "Numerous studies have associated increased COVID-19 severity and higher mortality rates with low CD4 counts in PLWH, likely a result of uncontrolled HIV infection." (PMID 40269243, 2025). "The risk of COVID-19 related hospitalization and death is consistently higher in those with low CD4 counts and in those with unsuppressed HIV due to drug resistance, or in PLWH not taking antiretroviral therapy (ART)." (PMID 40195984, 2025). "COVID-19 causes the overexpression of inflammatory cytokines and reduces cluster of differentiation 4+ (CD4+) T cell and CD8+ T cell counts, thus impairing cell-mediated immunity, paving the way for opportunistic fungal infections." (PMID 41322807, 2025). "CD4+ T helper cells are broadly important for antibody generation and reduction of T+ cells in COVID-19 that are associated with efficient antibody neutralization." (PMID 40724930, 2025). "For example, CD4+ T cells from patients with severe COVID-19 produce elevated levels of TNF-α, associated with impaired proliferative capacity of SARS-CoV-2-specific CD4+ T cells and increasing their susceptibility to activation-induced cell death." (PMID 41235245, 2025). "IL-21 is produced by follicular helper CD4+ T-cells that sustain B-cell functions, while IL-33 levels are associated with exacerbated pulmonary inflammation in COVID-19." (PMID 40573439, 2025). "Specifically, a reduction in CD4+ T cells of more than 60% leads to a critical state of COVID-19, causing serious alveolar epithelium damage and thus requiring hospitalization and mechanical ventilation." (PMID 40431602, 2025). "These synergistic mechanisms ultimately create a pathogenic milieu of hyperactivated CD4+ T cells and destabilized Tregs susceptible to functional collapse and apoptosis, fueling immunopathological cascades in severe COVID-19." (PMID 40806563, 2025). "Lymphopenia is a well-established hallmark of severe COVID-19, characterized by an absolute reduction in CD4+ and especially in CD8+ T cells." (PMID 40143288, 2025). "Subsequently, to determine the allelic effect of this OCR, we examined the allele-specific open chromatin effects in CD4 + T cells from hospitalized COVID-19 patients and convalescent individuals, respectively." (PMID 40759647, 2025). "A previous study involving 701 COVID-19 patients revealed a significant association between mortality and reduced counts of CD4+ T cells (≤ 500 cells/μl)." (PMID 39654887, 2024). "In summary, our data indicate that fatigue in convalescent COVID-19 patients with PASC is linked with altered CD4+ T cell counts." (PMID 37924472, 2024). "Sensitivity analysis further indicated that a low count of CD4+ T cells (< 100 cells/μl) was identified as a risk factor for mortality in COVID-19 patients." (PMID 39654887, 2024). "Univariable analysis revealed that elevated LDH; CRP; age; and high expression of CD39+CD45+, TIM3+CD39+CD4+CD45+, and TIM3+CD39+CD8+CD3+CD4+ cells were significantly associated with severe COVID-19 according to the WHO clinical progression scale." (PMID 38793691, 2024). "PWH with COVID-19 had higher VS and CD4 + cell counts and lower mortality compared to those hospitalised due to non-COVID-19-related causes, who more often were recently diagnosed with HIV and had ADEs." (PMID 38789972, 2024). "Although circulating SARS-CoV-2-specific CTLs are less consistently observed than CD4+ T cells, their presence is generally associated with better COVID-19 outcomes." (PMID 39450171, 2024).
COVID-19 (continued). "Our results suggest that strong CD4+ T- cell responses specific to selected “universal” SARS-CoV-2 epitopes were commonly associated with better COVID-19 outcomes." (PMID 38318166, 2024). "COVID-19-associated pulmonary aspergillosis was reported to reduce the number of CD4+ and CD8+ T cells leading to immune disruption in COVID-19 patients." (PMID 38835769, 2024). "Our study shows that PWH hospitalised due to non-COVID-19 causes had significantly lower CD4 + counts, a high proportion of ADEs and higher mortality (19%)." (PMID 38789972, 2024). "Within CD4+ T cell subtypes, individuals with critical COVID-19 also present high levels of CD4+ regulatory T cells (Tregs) that are implicated in the contraction of the inflammatory immune response developed during acute infection." (PMID 39257580, 2024). "The study findings showed severe COVID-19 is associated with signs of immunosuppression like reduced CD4+ T-cells and CD4/CD8 ratios." (PMID 38468605, 2024). "MR analysis results suggested that two markers of CD4+ TEM cells exhibit a direct causal relationship with the development of COVID-19." (PMID 39337460, 2024). "Some reports suggest that COVID-19 can trigger sarcoidosis and sarcoidosis-like autoimmune conditions, which are associated with CD4+ T cell-mediated inflammation and feature a high prevalence of chronic fatigue." (PMID 37924472, 2024). "ScRNA-seq analysis of CD4+ T-cells from 40 COVID-19 patients demonstrated that hospitalization caused an increase in the proportion of cytotoxic follicular helper cells and cytotoxic T helper cells, while reducing the population of regulatory T-cells." (PMID 38542251, 2024). "The diagnostic accuracy for COVID-19 severity, as measured by the area under the curve (AUC) for CD4+ T cells and NLR, was 0.715 (95% CI: 0.645-0.784) and 0.741 (95% CI: 0.675-0.807), respectively." (PMID 39679195, 2024). "Effective control of COVID-19 is associated with a type 1 CD4 phenotype, whereas type 2 is more common in patients with severe disease." (PMID 38793691, 2024). "Our study revealed that low levels of CD3+ cell (< 565.50 cells/μl), CD4+ cell (< 203.50 cells/μl), and NK cell (< 147.50 cells/μl) were associated with disease progression in COVID-19 patients receiving azvudine treatment." (PMID 39654887, 2024). "At DPSO 48, 5.3% of moderate COVID-19 patients exhibited high platelet counts (>300×109/L), associated with elevated total T-cells (26.4%), CD4 T-cells (24.4%), CD8 T-cells (36.9%), and Tregs (33.9%) compared to patients with normal platelet counts." (PMID 39628664, 2024). "PLWH, particularly those with high comorbidity burdens, uncontrolled viral loads, or low CD4+ T cell counts, are more susceptible to severe COVID-19 outcomes." (PMID 39460338, 2024). "Studies have also shown that higher proportions of virus-specific CD4+ T cells and T follicular helper (Tfh) cells are associated with milder COVID-19 symptoms, as well as a slower decline in humoral immunity." (PMID 39772110, 2024). "COVID-19 is known to cause a significant decline in CD4+ T cells, affect T-cell differentiation, and disrupt innate immune antigen presentation, as well as monocyte population imbalances." (PMID 39588145, 2024). "In summary, 5.3% of moderate COVID-19 unvaccinated patients show high platelet counts (> 300x109/L), which is linked to increased levels of total T-cells, CD4 and CD8 T-cells, and Tregs compared to patients with normal platelet counts." (PMID 39628664, 2024). "We utilized publicly accessible single-cell sequencing dataset to explore the underlying biological processes of CD4 T+ cells in elderly individuals with COVID-19." (PMID 39679195, 2024). "We observed a correlation between MWH with CD4 count <200 cells/μL and an increased risk of severe COVID-19, consistent with other studies in PWH." (PMID 38221982, 2024).
COVID-19 (continued). "Taken collectively, the pro-inflammatory response causing cardiotoxicity in COVID-19 is paralleled by a dysregulated immune response as seen by a reduction in CD4 + and CD8+ T-cells subsets in patients with severe disease." (PMID 38041432, 2024). "We demonstrated that the CD4 T-cell counts and mRNA vaccines are associated with seroconversion due to COVID-19 vaccination." (PMID 37112701, 2023). "A prior study among vaccinated PWH found that those with moderate/severe immunodeficiency (CD4 < 350 cells/mm3) had a 59% increased risk of severe breakthrough COVID-19 illness (requiring hospitalization) compared with people without HIV34." (PMID 37996521, 2023). "Compared to healthy controls, the disease ssGSEA score showed that COVID-19 was most significantly associated with memory CD4 T cells (P < 0.0001), whereas AMI was most significantly associated with myeloid-derived suppressor cells (MDSC) (P < 0.01)." (PMID 38022594, 2023). "Several studies of acute and convalescent COVID-19 patients have revealed that T cell responses are associated with reduced severity of the disease, implying that CD4+ T and CD8+ T cell responses are important for the resolution and the control of infection." (PMID 38004749, 2023). "Upper quartile ratios of CD4+ to CD8+ have been implicated in higher COVID-19 mortality rates during the acute phase due to lower CD8+ T cell expansion." (PMID 37175761, 2023). "The researchers discovered lymphopenia in severe COVID-19 patients was associated with decreased T cell counts, specifically CD4+ and CD8+." (PMID 37377785, 2023). "People living with HIV (PLWH) are considered at high risk of severe COVID-19, mainly in the case of low CD4+ counts or unsuppressed viremia." (PMID 37513709, 2023). "In humans, abundant CD4+CD154+ T cells are associated with severe COVID-19, particularly in T cells producing abundant proinflammatory cytokines, including interferon-γ (IFNγ), tumor necrosis factor, interleukin-2 (IL-2) and/or interleukin-21 (IL-21)." (PMID 37856551, 2023). "In PWH on antiretroviral therapy with well controlled HIV-replication and preserved CD4+ cell counts, underlying comorbidities and other general risk factors for severe COVID-19-related outcomes appear to play a larger role than HIV-related factors." (PMID 37199566, 2023). "We finally found that the CD4 T-cell counts and vaccine type are associated with seroconversion due to COVID-19 vaccination." (PMID 37112701, 2023). "Among them, SARS-CoV-2-specific CD4+ T cells were most strongly associated with reduced disease severity in COVID-19." (PMID 37601070, 2023). "Among COVID-19– participants, we observed clear associations between nadir CD4 and non–SARS-CoV-2 responses." (PMID 36805331, 2023). "Factors associated with CD4+ T-lymphocyte count after the administration of the Chinese inactivated COVID-19 vaccine." (PMID 36936962, 2023). "HIV-related factors, such low CD4 T-cell counts, detectable viral load, opportunistic infections, or neoplastic diseases are independent risk factors for severe COVID-19." (PMID 37242997, 2023). "As such, the higher vulnerability of the elderly to severe COVID-19 has been linked to reduced pre-existing cross-reactive CD4+ T cell responses." (PMID 38343437, 2023). "Individual case considerations indicate that patients older than 60 years, with severe concomitant diseases, and low CD4 T-cell nadir counts who are at high risk of fatal course of COVID-19 can fail vaccination." (PMID 37242997, 2023). "Here, we propose that the alterations in immune responses associated with severe COVID-19 are at least partially triggered by infection of CD4+ T helper cells by SARS-CoV-2 and consequent dysregulation of immune function." (PMID 37523305, 2023). "Among the COVID-19– participants, female sex, older age, and lower nadir CD4 were associated with unique repertoire shifts." (PMID 36805331, 2023).
COVID-19 (continued). "Higher COVID-19 vaccine hesitancy was associated with older age, lower educational level, chronic diseases, lower CD4 counts, and psychological factors, such as severe anxiety and depression." (PMID 38140668, 2023). "Positive studies: compared to recovered COVID-19, significant differences in genes linked to cell cycle, CD4+ cells, genes related to monocyte and myeloid cell function." (PMID 37342500, 2023). "We use DISCERN to detect two unseen COVID-19-associated T cell types, cytotoxic CD4+ and CD8+ Tc2 T helper cells, with a potential role in adverse disease outcome." (PMID 37730638, 2023). "While multiple host factors were associated with unique non–SARS-CoV-2 humoral responses among COVID-19– participants, only nadir CD4 and BMI were associated with SARS-CoV-2 profile shifts in the COVID-19+ cohort." (PMID 36805331, 2023). "COVID-19 is associated with lymphopenia, which manifests as a reduction in CD4+ and CD8+ T-cell subsets." (PMID 37533853, 2023). "In correspondence with this work, a decrease in the percentage of CD4+ cells with a Th1 phenotype was detected in patients with COVID-19, which has been associated with a bad prognosis and resolution of the disease." (PMID 38005968, 2023). "The level of CD8+ T cells reflects the severity of the patient's disease, while reduced levels of CD4+ T cells are only independently associated with increased in-hospital mortality in COVID-19 patients." (PMID 37705735, 2023). "A unique SARS-CoV-2 humoral response was also associated with lower nadir CD4 among the COVID-19+ cohort." (PMID 36805331, 2023). "Another example is MUC20, at which we identified a Neanderthal-introgressed eQTL that increases MUC20 expression in SARS-CoV-2-stimulated CD4+ T cells and decreases COVID-19 susceptibility." (PMID 37558883, 2023). "Increased cytokine levels (IL-6, IL-10, and TNF-α) and decreased IFN-γ expression in CD4+ T cells have been associated with severe COVID-19 in adults." (PMID 37602239, 2023). "Five hub genes were differentially expressed in COVID-19 patients compared to controls, and they were associated with the activation of regulatory T cells, NK cells, and CD4 memory T cells." (PMID 37426635, 2023). "A higher Firmicutes to Bacteroidota ratio is associated with a lower spike-specific CD4+ T cell response, indicating a lower response to COVID-19 vaccination, agreeing with our observation." (PMID 37705931, 2023). "Lymphocytopenia is the hallmark of COVID-19 severity, but elevated levels of CD4+T and CD8+T cells were associated with milder disease conditions." (PMID 37243203, 2023). "The higher odds of booster dose reception among PWH with CD4 levels below 200 cells/μL, aligning with public health recommendations, is encouraging due to their increased susceptibility to severe COVID-19 outcomes." (PMID 38250857, 2023). "We found that in PWH on ART with well controlled HIV infection and preserved CD4+ cell counts, underlying comorbidities and other general risk factors for severe COVID-19-related outcomes play a larger role than HIV-related factors." (PMID 37199566, 2023). "A recent study showed that low levels of CD4+T cells, high levels of IL-6, and inflammatory cytokines in COVID-19 patients increase the risk of severe liver injury." (PMID 36671484, 2023). "Here, we found that the CD4 T-cell counts are associated with seroconversion in COVID-19-vaccinated PLWH." (PMID 37112701, 2023). "Previous studies have shown dysregulation of innate and adaptive immune cell compartments in patients with convalescent COVID-19, suggesting an association between CD4+ and CD8+ T cell response and disease severity." (PMID 37600824, 2023). "Rapid induction of virus-specific CD4+ cells has been associated with a milder COVID-19 course, and their absence was linked to fatal outcomes in patients with COVID-19." (PMID 36680091, 2022). "Consistently, defective GC formation is associated with CD4+ T cell depletion in the lymph nodes of severe COVID-19 patients." (PMID 35581387, 2022).